GRAMD2B (GRAM domain containing 2B)
Synonyms: GRAMD3; NS3TP2; FLJ21313
Tractability: PROTAC: ubiquitination databases record sites on it.
Gene: Protein-coding gene on chromosome 5 (126,360,132 to 126,496,494, forward strand). Ensembl gene ENSG00000155324.
Subcellular location (Human Protein Atlas): Cytosol; Golgi apparatus; Nucleoplasm
Gene Ontology:
Molecular function: identical protein binding; protein binding
Cellular component: cytoplasmic microtubule; cytoplasm
Genetic constraint (gnomAD): Loss-of-function variants: 13 observed, 16.88 expected, observed/expected ratio (o/e) 0.77, 90% interval 0.5 to 1.22. The upper end of that interval is the gene's LOEUF score, 1.22, which puts it in group 5 of 6, group 1 being the genes least tolerant of losing a copy. Missense variants: 172 observed, 201.75 expected, observed/expected ratio (o/e) 0.85, 90% interval 0.75 to 0.97. Synonymous variants: 65 observed, 75.38 expected, observed/expected ratio (o/e) 0.86, 90% interval 0.7 to 1.06.
Homologues: Orthologues: chimpanzee GRAMD2B (95% identical), macaque GRAMD2B (90% identical), pig GRAMD2B (86% identical), guinea pig GRAMD2B (83% identical), mouse Gramd2b (82% identical), rat Gramd2b (82% identical), dog GRAMD2B (80% identical), rabbit GRAMD2B (76% identical), tropical clawed frog gramd2b (46% identical), Drosophila melanogaster GramD1B (20% identical), Caenorhabditis elegans ZC328.3 (17% identical). Paralogues in human: GRAMD2A (25% identical), GRAMD1A (25% identical), GRAMD1B (24% identical), GRAMD1C (21% identical).
Diseases named in the same sentence as GRAMD2B in open-access papers:
GRAMD2B is named in the same sentence as 6 diseases in open-access papers, as found by Europe PMC text mining. Sharing a sentence is not in itself a finding about the gene and the disease.
GRAMD2B shares sentences with these, for which no sentence is quoted: cerebrovascular disease (1 paper); cognitive decline (1); hypopharyngeal cancer (1); ischemic stroke (1); lung adenocarcinoma (1); translocation renal cell carcinoma (1).